HMGCS2 (3-hydroxy-3-methylglutaryl-CoA synthase 2)
Diseases named in the same sentence as HMGCS2 in open-access papers (continued):
Sharing a sentence is not in itself a finding about the gene and the disease.
tumor (continued). "In human HCC cell lines, knockdown of HMGCS2 increases tumor growth and cell migration, while HMGCS2 overexpression decreases cell proliferation and increases apoptosis." (PMID 35860662, 2022). "Collectively, dysregulation of the HMGCS2 gene altered sorafenib-induced inhibition of tumor migration through regulating expressions of epithelial and mesenchymal markers." (PMID 36432116, 2022). "Meanwhile, HMGCS2 transcription is negatively regulated by mechanistic target of rapamycin complex 1 (mTORC1) kinase and tumor-derived interleukin-6 (IL-6), presumably suppressing PPARα." (PMID 36432618, 2022). "We observed that HMGCS2 knockdown cells possessed significantly greater tumor growth and enhanced tumor weight and tumor size compared with the control group." (PMID 32635582, 2020). "Since cancer cells use the ketogenesis as an alternative energy source, constitutive expression of HMGCS2 as the first step of this chain is essential for tumor development." (PMID 32155177, 2020). "Under KD feeding, a higher tumor growth rate was observed in HMGCS2 knockdown tumors, which had increased lipid synthesis-related marker expression and a positive correlation between lipid quantity and tumor weight." (PMID 32635582, 2020). "Our data reveal that mice fed a KD inhibited tumor growth, which was accompanied by increased HMGCS2 expression." (PMID 32635582, 2020). "With our new findings, it is possible that not only decreased ketone production but also upregulated de novo lipogenesis in HMGCS2 knockdown HCC cells enhanced tumor growth." (PMID 32635582, 2020). "To gain more insight into the gene-diet interaction in the treatment of HCC, we showed that HMGCS2 knockdown HCC tumors had increased tumor size when a KD was used." (PMID 32635582, 2020). "Surprisingly, we found a reverse correlation between tumor size and HMGCS2 protein expression in the KD-fed mouse group." (PMID 32635582, 2020). "Next, we analyzed the correlation between the tumor size and HMGCS2 protein expression among the tumors of the KD-fed mice group." (PMID 32635582, 2020). "On the other hand, HMGCS2-overexpressing Huh-7 cells showed a lower tumor formation ability than control cells." (PMID 31779269, 2019). "In the in vivo mouse model, we found that HCC cells with HMGCS2 downregulation showed an increased tumor growth ability." (PMID 31779269, 2019). "In this study, we aimed to seek evidence to elucidate the possible relationship between HMGCS2 and tumor angiogenesis in development of CRC." (PMID 31355161, 2019). "On the contrary, the other three downregulated genes including HMGCS2, HSD11B2, and OGDHL in higher immune score and stromal score groups indicated higher expressions of these genes were associated with more tumor purity and prognostic advantages." (PMID 31886185, 2019). "HMGCS2 is the rate-limiting enzyme of ketogenesis, which is vital for tumor initiation or metastasis." (PMID 31355161, 2019). "Quantification of the ketone body concentration indicated that HMGCS2-regulated tumor growth occurs in a ketone-dependent manner." (PMID 31779269, 2019). "It has been reported that MMP1 overexpression has an important role in promoting tumor cell invasion and HMGCS2 silence promoted tumor cells metastatic via Epithelial-Mesenchymal Transition (EMT) process and the activation of ERK/c-Jun signaling pathway." (PMID 31074374, 2019). "HMGCS2 plays a critical role in tumor progression, since overexpression increases ketone body production, thereby favoring growth and motility of cancer cells." (PMID 29662633, 2018). "Accordingly, an anticancer drug that can target CD36, TSP-1, and HMGCS2 during tumor treatment has great potential for slowing or blocking tumor metastasis." (PMID 29914089, 2018). "Ketone bodies are also major energy sources for mitochondria and they are synthesized in tumour stroma with the help of enzymes, such as HMGCS2, HMGCL, BDH1, and re-utilised in tumour cells." (PMID 28373964, 2017).
tumor (continued). "Second, our data demonstrated that HMGCS2 had a critical role in enhanced tumor migration, invasion and metastatic phenotypes through metabolic-independent mechanism in vitro." (PMID 27816970, 2017). "In this study, we found that HMGCS2 was up-regulation in tumor tissue compared with normal tissue, and its expression was strongly correlated with poor clinically outcomes in CRC and OSCC patients." (PMID 27816970, 2017). "Notably, the acidic isoform of HMGCS2 detected in IACs is co-migrated with the basic variants of alpha-enolase, a protein that is highly expressed in all tumor subtypes analyzed and, as a result, may mask the identification of HMGCS2 by 2D PAGE in these samples." (PMID 25389781, 2014). "3-Hydroxy-3-methylglutaryl-CoA synthase 2 (HMGCS2), a mitochondrial enzyme involved in ketogenesis, has been linked to tumor progression, but its role in CCA remains unclear." (PMID 41960367, 2026). "In most other cancers, however, HMGCS2 functions as a tumor suppressor." (PMID 40305364, 2025). "When the cancer-associated fibroblasts induce HMGCS2 in tumor cells, the result is not ketogenesis but rather cholesterol and steroid synthesis." (PMID 40305364, 2025). "The involvement of ketogenesis, and hence HMGCS2, in cancer is complex because of the multiple biological functions of the ketone bodies that may be either tumor-promotive or tumor-suppressive." (PMID 40305364, 2025). "As such, HMGCS2 functions as a tumor suppressor in this organ." (PMID 40305364, 2025). "LOC101928222 or HMGCS2 knockdown reduced tumor-initiating capacity of CRC cells in nude mice, overexpression of HMGCS2 or IGF2BP1 could rescue the tumor-initiating capacity of LOC101928222 or HMGCS2-knockdown CRC cells." (PMID 38965575, 2024). "HMGCS2, also known as 3-hydroxy-3-methylglutaryl-coenzyme A synthase 2, is a key ketogenic enzyme responsible for facilitating ketone production and regulating tumor proliferation and metastasis." (PMID 38327905, 2023). "In addition, HMGCS2 is associated with tumor immune infiltration and microenvironment, and KIRC patients with low expression of HMGCS2 have worse prognosis." (PMID 37670031, 2023). "Moreover, HMGCS2 expression was related to tumor stage in BRCA, KIRC, LIHC, THCA, SKCM, BLCA, and KICH, Furthermore, Kaplan–Meier survival analysis was performed to assess the association of HMGCS transcription levels with KIRC and LIHC." (PMID 37670031, 2023). "In the univariate analysis, consistent with previous reports that PAK4 is an indicator of aggressive tumor behavior and potentially affects patient outcomes, PAK4 and HMGCS2 expression was significantly associated with relapse-free (RFS) and overall survival (OS)." (PMID 37591884, 2023). "In addition, reduced transcription of the HMGCS2 gene by DNA hypermethylation has been shown to reduce ketogenesis and facilitate tumor cell motility in clear cell renal cell carcinoma (ccRCC)." (PMID 36432618, 2022). "HMGCS2 is an enzyme involved in catalyzing ketosis in mitochondria, which not only determines the ketogenic ability of the colon, but also provides lipid-derived energy for tumor cells, and affects tumor development and migration." (PMID 36419192, 2022). "We further investigated whether the tumor inflammation was influenced by HMGCS2 expression in response to KD treatment." (PMID 32635582, 2020). "Notably, incubation of tumor cells with CAF-conditioned medium alone also resulted in an upregulation of HMGCS2 and AKR1C3 suggesting a paracrine communication between tumor epithelial cells and CAFs." (PMID 31980029, 2020). "Moreover, we further analyzed the correlations between each lipid species and tumor weight among HMGCS2 knockdown tumors." (PMID 32635582, 2020). "We also evaluated the tumor growth ability of HMGCS2 overexpression under KD feeding." (PMID 32635582, 2020). "Thus, using a KD will increase HMGCS2 expression, and thereby, enhance ketone production to inhibit tumor growth." (PMID 32635582, 2020).
tumor (continued). "Indeed, we found that the tumor sizes in KD-fed mice were negatively correlated with the HMGCS2 protein expression level." (PMID 32635582, 2020). "The results showed that the tumor weight in the HMGCS2 overexpression group was slightly lower than that in the control group, while the amounts of PCNA and Ki-67 nuclear signal were not significantly changed between the HMGCS2 overexpression and the eGFP control tumors." (PMID 32635582, 2020). "Together, our data indicated that HMGCS2 plays an important role in tumor angiogenesis." (PMID 31355161, 2019). "Furthermore, we found three lipid-metabolism related genes HMGCS2, GPX2 and CD36 associated with the tumor immune microenvironment were significantly correlated with prognosis." (PMID 31074374, 2019). "Genes related to lipid metabolism and immune response that are associated with poor prognosis were discovered including HMGCS2, GPX2 and CD36, which may provide clues for tumor biomarkers or therapeutic targets." (PMID 31074374, 2019). "The aim of this study is to determine the relationship between HMGCS2 and tumor angiogenesis." (PMID 31355161, 2019). "Further analysis showed that HMGCS2 expression was negatively correlated with expression and was correlated with microvessel density (Spearman R=-0.8696, p<0.001), implying that HMGCS2 is a critical factor involved in tumor angiogenesis." (PMID 31355161, 2019). "HMGCS2 knockdown HCC cells showed enhanced tumor growth in a xenograft mouse model." (PMID 31779269, 2019). "Some studies have shown that HMGCS2 may relate to the progression of cancer and play a key role in enhancing the phenotype of tumor migration, invasion, and metastasis through an independent metabolic mechanism in vitro." (PMID 31660141, 2019). "The results showed that knockdown of HMGCS2 enhanced tumor formation." (PMID 31779269, 2019). "Comparison of these data suggest that the function of HMGCS2 may depend on tumor cell type." (PMID 34298684, 2021). "Therefore, we hypothesized that the expression of the ketogenesis rate-limiting enzyme HMGCS2 may be upregulated, and thereby, increase ketone production to inhibit tumor growth." (PMID 32635582, 2020). "HMGCS2 may function as either an oncogene or a tumor suppressor in various human cancers." (PMID 31886185, 2019). "In addition, knockdown of HMGCS2 expression in HT29 cells drastically increased tumor angiogenesis." (PMID 31355161, 2019). "We analyzed the differences in the expression of nomogram model genes (HMGCS2, HNRNPU, RAN) with regard to clinical pathological factors (T, N, M, normal vs. tumor)." (PMID 39453509, 2024). "We also analyzed the differences in the expression of nomogram model genes (HMGCS2, HNRNPU, RAN) across clinical pathological factors (T, N, M staging, normal vs. tumor)." (PMID 39453509, 2024). "COL5A2, HMGCS2 and ITGA5 expressed in the tumour compartment and cytoplasmatic as well as WNT9Bnuc in the stroma were favourable prognostic factors for OS (p < 0.05) in univariate analysis." (PMID 38361045, 2024). "Since overexpression of each of these genes inhibited growth/proliferation and migration/metastasis of these cancer cells, genes for ketogenic enzymes such as HMGCS2, ACAT1, HMGCL, and BDH are suggested to be potential tumor suppressors." (PMID 36432618, 2022). "Seven genes, PFKFB4, ALDOA, EGLN3, EHHADH, GAPDH, HMGCS2, and ENO2, related to tumor FDG uptake were revealed to have a good prognostic value for survival in HCC." (PMID 35174098, 2022). "HMGCS2 is downregulated in CRC, serving as a critical downstream target of SLC38A4 to regulate tumor cell metabolism." (PMID 35909892, 2022). "We found that the expression levels of HMGCS2 and SLC22A1 were higher in tumor-adjacent tissues; while the expression levels of G6PD were higher in HCC tissues." (PMID 35392063, 2022).
tumor (continued). "In agreement with our findings, HMGCS2 was previously reported to be significantly down-regulated in HCC patients with high alpha-fetoprotein (AFP), tumor size >5 cm, multinodular, advanced tumor staging including BCLC, TNM and CLIP." (PMID 34830779, 2021). "Here, we report that KD feeding upregulates HMGCS2 expression and inhibits HCC tumor growth, while a reverse correlation between tumor size and HMGCS2 expression was observed." (PMID 32635582, 2020). "While down-regulation of genes such as CYP4A11, PLA2G4A, PLA2G3, LTC4S, CYP27A1, HMGCS2 and PDPK1 reduced patient overall survival time in most tumor types." (PMID 31074374, 2019). "A Random Forest Classifier model showed that, in eight of the nine tumor cohorts, these patterns were largely determined by a small subset of transcripts, comprised of DHCR24, HMGCS2, PMVK and ACAT1/2." (PMID 31242205, 2019). "This study demonstrated the correlation between the increased mRNA levels of HMGCS2 and poor clinical outcomes as well as grade malignancy in colorectal cancer (CRC) and oral squamous cell carcinoma (OSCC) tumor biopsy from affected patients." (PMID 29966227, 2018). "Additionally, the HMGCS2 gene is downregulated in CRC, serving as a critical downstream target for SLC38A4 to regulate tumor metabolism." (PMID 39114022, 2024). "Wang et al3 found that KD up-regulates HMGCS2 expression and hinders the growth of HCC tumor; in the meantime, a negative correlation between tumor size and HMGCS2 expression was observed." (PMID 39344752, 2024). "While the expression of HMGCS2 was very clear in tumour cells, it was predominantly negative in the stroma." (PMID 38361045, 2024). "Our study showed that simvastatin is a promising treatment for HMGCS2‐induced resistance and may affect tolerance delay when used in combination with NTRK‐TKI at clinical concentrations in an NTRK‐rearranged tumor." (PMID 38923428, 2024). "The role of HMGCS2 was evaluated in a pan-cancer multi-database using R language, and HMGCS2 was lowly expressed or not differentially expressed in all tumor tissues compared with normal tissues." (PMID 37670031, 2023). "Although HMGCS2 is currently considered a potential biomarker and a key mediator in various human malignancies, there is no comprehensive report on its anti-tumor function in pan-cancer." (PMID 37670031, 2023). "Furthermore, the tumor suppressing function of miR-107 has been previously reported in HCC via targeting oncogenic genes, including RGS4, HMGA2, HMGCS2, cofilin-1, and Wnt/β-catenin." (PMID 37744274, 2023). "Consistent with animal studies, immunoblotting analysis of liver tissues obtained from HCC patients indicated higher levels of PAK4, total-, phospho-, and nuclear-NCoR1, and lower levels of HMGCS2 in tumor compared to non-tumorous tissues." (PMID 37591884, 2023). "Sorafenib treatment also inhibited tumor metastasis by inhibiting the EMT pathway; however, whether downregulation of the HMGCS2 gene altered sorafenib-induced EMT inhibition remains unknown." (PMID 36432116, 2022). "On the other hand, the amounts of fatty acids, triglycerides, and cholesterol in the tumor mass were not significantly different between the HMGCS2 overexpression group and the eGFP control group." (PMID 32635582, 2020). "SIRT3 can deacetylate and activate various mitochondrial metabolic enzymes involved in TCA and FAO enzymes, including LCAD, 3-hydroxy-3-methylglutaryl CoA synthase 2 (HMGCS2), isocitrate dehydrogenase 2 (IDH2) and glutamate dehydrogenase (GDH) to block the supply of glycolysis to the tumor cells." (PMID 33109235, 2020). "We then analyzed whether CAF-induced upregulation of HMGCS2 and AKR1C3 was due to paracrine signaling between tumor cells and CAFs." (PMID 31980029, 2020). "Despite the strong research concerning the function of HMGCS2 in tumor, data are lacking in the potential relationship between HMGCS2 and tumor angiogenesis." (PMID 31355161, 2019).
tumor (continued). "During the course of tumor development we observed a slight but significant decrease of LIN28A stem cell marker typical for HBL and an increase of 3-hydroxy-3-methylglutaryl-CoA synthase 2 HMGCS2 and MEP1A." (PMID 29662633, 2018). "Whether these differences among the various studies in terms of whether or not HMGCS2 is a tumor suppressor or tumor promoter in the colon can be explained by the expression status of PPARα in the tumor tissue is yet to be investigated." (PMID 40305364, 2025). "Without affecting tumour growth, a carbohydrate‐free diet improved tibialis anterior myofibre diameter (+16.5 ± 3.5%, P = 0.0089), circulating ketone bodies (+333.0 ± 117.6%, P < 0.0001) and Hmgcs2 expression (+106.5 ± 36.1%, P < 0.0001) in PDAC mice." (PMID 38632714, 2024). "Downregulation of 3-hydroxy-3-methylglutaryl-CoA synthase 2 (HMGCS2) reduces ketone production, enhances the c-Myc/cyclinD1 and EMT signaling pathways, and inhibits caspase-dependent apoptosis pathways, which promotes tumor proliferation, migration and xenograft tumorigenesis in various cancers." (PMID 34557495, 2021). "Among 6 significant hub genes, significantly decreased AGPAT9, AQP7, HMGCS2, KLF15, PPARGC1A mRNA expressions were found in ccRCC tissues compared with adjacent normal tissues, while MLXIPL mRNA expression was significantly elevated in tumor samples compared with normal samples." (PMID 31493764, 2019). "In addition, these results suggested our study showed not an additive effect resulting from the anti‐tumor effect of statins, but resulting from statin induce overcoming resistance mechanism of NTRK‐TKIs from HMGCS2 in our study." (PMID 38923428, 2024).